ATF4 (activating transcription factor 4)
Diseases named in the same sentence as ATF4 in open-access papers (continued):
Sharing a sentence is not in itself a finding about the gene and the disease.
ischemic stroke (6 papers, 2018 to 2024). A stroke disorder caused by obstruction of blood flow to the brain, due to thrombotic (local blood clot formation) or embolic (due to a blood clot or other material traveling from another site) event. "The mouse model of ischemic stroke with ATF4 deletion shows the resistance to the oxidative stress-induced death in neurons." (PMID 38321473, 2024). "ATF4, similar to its role in ischemic stroke, becomes a significant target of inhibiting neuronal death in several rodent models of hemorrhagic stroke." (PMID 38321473, 2024). "Also, ATF4 is involved in the expressions of Bax, Bcl-2 and ER stress-related genes during ischemic stroke." (PMID 38321473, 2024). "The UPRmt-related protein ATF4 has been determined to be the pro-death transcription factor promoting the progression of ischemic stroke although it plays neuroprotective role in the early stage of ischemic stroke." (PMID 38321473, 2024). "The interacting partners of HDAC4, MEF2, Runx2, SRF, HP1, ATF4, and NF-κB might also mediate its role in inhibiting neuronal death and promoting angiogenesis and neurogenesis in ischemic stroke." (PMID 30208931, 2018). "Studies have shown that mice lacking ATF4 have smaller infarcts, improved behavioral outcomes, and increased resistance to neuronal cell death in the context of ischemic stroke, highlighting the pro-death role of increased ATF4 expression." (PMID 37600520, 2023).
osteoarthritis (6 papers, 2018 to 2026). A noninflammatory degenerative joint disease occurring chiefly in older persons, characterized by degeneration of the articular cartilage, hypertrophy of bone at the margins and changes in the synovial membrane. "Therefore, an important question arising is whether activation of the ISR and its associated ectopic expression of ATF4 and its downstream targets such as Sox9 may underlie common skeletal diseases such as intervertebral disc degeneration and osteoarthritis." (PMID 30024379, 2018). "ATF4 serves as a major transcription factor regulating osteoarthritis (OA) and knee osteoarthritis (KOA) under ER stress conditions." (PMID 40777108, 2025). "•Knockdown of ATF4 improves osteoarthritis by inhibiting ferroptosis in the DMM-induced osteoarthritis model." (PMID 40782567, 2025). "In skeletal system research, both primary osteoblast cultures and mouse models of osteoarthritis or steroid-induced osteonecrosis have been utilized to examine ATF4’s role in bone remodeling." (PMID 40777108, 2025). "The present study evaluated whether the lack of histone deacetylase 4 (HDAC4) increases endoplasmic reticulum stress-induced chondrocyte apoptosis by releasing activating transcription factor 4 (ATF4) in human osteoarthritis (OA) cartilage degeneration." (PMID 38879481, 2024). "•ATF4 transcriptionally activates NUPR1, offering a novel therapeutic strategy to mitigate ferroptosis and slow osteoarthritis progression." (PMID 40782567, 2025). "Thus, it is likely that NUPR1 represents one of several important mediators, rather than the sole effector of ATF4′s actions in osteoarthritis." (PMID 40782567, 2025).
prion disease (6 papers, 2015 to 2024). A transmissible disease that is caused by a protein that is able to induce abnormal folding of normal cellular proteins, leading to characteristic spongiform brain changes, which are associated with neuronal loss without an inflammatory response. "The involvement of the PERK-eukaryotic initiation factor 2 (eIF2α)-ATF4 pathway in prion diseases is still controversial." (PMID 37152434, 2023). "The treatment of a mouse model of prion disease with this inhibitor induced a repression of protein synthesis associated with decreased levels of p-PERK, p-eIF2α, ATF4 and CHOP, showing the neuroprotective effect of GSK2606414." (PMID 32854418, 2020). "Furthermore, in a cellular model of prion disease, the overexpression of ATF4 or an active mutant form of ATF6 prevented PrP aggregation." (PMID 32854418, 2020). "Therefore, additional stimuli, possibly from activated microglia or astrocytes, may be required for the full activation of the PERK-eIF2α-ATF4 pathway in the brains of prion-infected mice to produce the neurodegeneration observed in prion diseases." (PMID 32479530, 2020). "In a prion disease model, treatment with ISRIB reduced inhibition of protein translation as measured by the levels of ATF4, a marker of ISR activity, and extended survival by approximately 1 week." (PMID 27781164, 2016). "Since ER stress has previously been shown to be involved in prion disease, we examined the levels of phosphorylated PERK (p-PERK), phosphorylated eIF2α (p-eIF2α), and ATF4 in both paradigms of PrPC-dependent neurotoxicity." (PMID 25710374, 2015).
thyroid cancer (6 papers, 2018 to 2025). "Zong and collaborators demonstrated that Nrf2 affected CHOP expression by modulating the binding of ATF4 to the CHOP promoter in thyroid cancer cells, and the accumulation of Nrf2 negatively regulated CHOP induction." (PMID 30515102, 2018). "Gene expression analysis in a cohort of patients with thyroid cancer showed a significant positive correlation between WWTR1 and ATF4 (Spearman correlation r=0.33, p<0.001)." (PMID 40667288, 2025). "In addition, in thyroid cancer B-CPAP cells, Naringin regulates PERK/eIF2 α/ATF4/CHOP axis can upregulate the expression of E-cadherin and downregulate the expression of N-cadherin and Vimentin, which can significantly inhibit tumor cell metastasis and invasion." (PMID 37663256, 2023).
ZIKV infection (6 papers, 2018 to 2024). "Specifically, the activation of the ISR kinases during ZIKV infection would lead to a shutdown of cap-dependent translation, increase translation of ATF4, and subsequent activation of ATF3." (PMID 39212382, 2024). "We recently determined that ATF3 is activated by ATF4, the master regulator of the integrated stress response, and functions to promote the expression of select immune response genes to restrict ZIKV infection." (PMID 39065267, 2024). "In this study, we show via inhibitor and RNA interference approaches that ZIKV infection initiates the integrated stress response pathway to activate ATF4 which in turn induces ATF3 expression." (PMID 39212382, 2024). "We identified the ISR pathway as the upstream signaling cascade leading to ATF3 activation during ZIKV infection with ATF4 as the direct effector of ATF3 in this pathway." (PMID 39212382, 2024). "During ZIKV infection, we observed increased levels of ATF4 RNA and protein, and this increase in ATF4 expression led to the activation of ATF3." (PMID 39212382, 2024). "In ZIKV infection, we found that phospho-eIF2α is still functional as a translational blocker but is unable to activate ATF4 translation." (PMID 34106769, 2021). "Therefore, ATF3 and ATF4 have opposing roles that together modulate the cellular response to ZIKV infection." (PMID 39212382, 2024). "ZIKV infection upregulated ATF4 and ATF3 protein and RNA abundance." (PMID 39212382, 2024). "In this study, we used ISR-specific inhibitors, and RNA interference (RNAi) approaches to show that during ZIKV infection, the ISR pathway stimulated ATF4 expression which directly activated ATF3." (PMID 39212382, 2024). "ATF4 protein and mRNA levels on the other hand increased in ZIKV-infected cells treated with the PERK inhibitor (data not shown), which was likely the result of activation of the other ISR kinases, such as PKR, in response to ZIKV infection." (PMID 39212382, 2024). "As expected, during ZIKV infection, ATF3 mRNA and protein were expressed, while in the presence of ISRIB, the levels of ATF3 mRNA decreased, consistent with the effect of ISRIB on ATF4 protein abundance." (PMID 39212382, 2024). "Thus, we next investigated if ATF4, the master regulator of the ISR pathway, was the upstream activator of ATF3 during ZIKV infection." (PMID 39212382, 2024). "However, ZIKV infection failed to induce ATF4 expression at 48 and 72 hpi despite dramatic increases in eIF2α phosphorylation." (PMID 34106769, 2021). "Administration of a PERK inhibitor was reported to correct cortical neurogenesis during ZIKV infection without affecting viral replication, suggesting that PERK and ATF4 activation may contribute to fetal microcephaly associated with congenital ZIKV infection." (PMID 32138181, 2020). "When we inhibited the ISR pathway during ZIKV infection using ISRIB, a broad ISR inhibitor, or GSK2606414, a PERK inhibitor (data not shown), ATF4 protein expression was reduced, and ATF3 mRNA levels were negligible (and data not shown)." (PMID 39212382, 2024).
acute kidney injury (5 papers, 2016 to 2024). Sudden and sustained deterioration of the kidney function characterized by decreased glomerular filtration rate, increased serum creatinine or oliguria. "In conclusion, our findings identify BRD4 as a key regulator of overexpression of the ATF4 and XBP1 UPR genes after acute kidney injury induced by IRI." (PMID 38481808, 2024).
Atrophy (5 papers, 2015 to 2022). Any weakening or degeneration, especially through lack of use. "Mechanistically, Thbs1 binds and activates the endoplasmic reticulum stress effector PERK, inducing its downstream transcription factor ATF4 and causing lethal autophagy-mediated cardiac atrophy." (PMID 34168130, 2021). "In the starvation induced atrophy model, ATF4 can increase the expression levels of downstream CDKN1A and GADD45 α." (PMID 34276308, 2021). "Third, a variety of impairments in skeletal muscle protein synthesis have been implicated as important contributing factors in age-related muscle atrophy, and we hypothesized that ATF4-mediated gene expression might have a capacity to reduce protein synthesis in skeletal muscle." (PMID 26338703, 2015). "The potential role of ATF4 in age-related muscle atrophy had not been investigated." (PMID 26338703, 2015).
bladder cancer (5 papers, 2013 to 2022). "We have also reported that proteasome inhibitors activate both Nrf2 and ATF4 and cooperatively induce the expression of the cystine transporter xCT in bladder cancer cells via Nrf2 binding to ARE and ATF4 binding to amino acid response elements (AAREs), respectively." (PMID 32079324, 2020). "We also discovered that ER stress component, like HSPA5, ERN1, ATF4 and DDIT3, increased when the human bladder cancer cells were treated with BIX-01294." (PMID 25685062, 2015). "In the present study, T24 bladder carcinoma cells showed the biphasic increases of UPR genes ATF3 and ATF4." (PMID 23560094, 2013).
Coffin-Lowry syndrome (5 papers, 2017 to 2025). A rare X-linked syndromic intellectual disability characterized by global development delay, postnatal growth retardation leading to short stature, facial dysmorphism, short hands with tapering fingers and progressive skeletal abnormalities including kyphoscoliosis and pectus carinatum/excavatum. "Mutations of RSK2, which can phosphorylate ATF4, causes the Coffin-Lowry syndrome, with its characteristic skeletal disorders." (PMID 29213288, 2017). "ATF4 is involved in various diseases related to bone metabolism, including Coffin-Lowry Syndrome." (PMID 38428406, 2024). "The study indicates that ATF4 is a critical regulator of osteoblast differentiation and function, and suggests that absence of ATF4 phosphorylation by RSK2 may part to the bone phenotype of Coffin‐Lowry syndrome." (PMID 33205007, 2020).
diabetic nephropathy (5 papers, 2021 to 2025). "Taken together, our results suggest that QDD effectively alleviates diabetic renal injuries and fibrosis by inhibiting the PERK-eIF2α-ATF4 pathway and promoting autophagy in diabetic nephropathy." (PMID 36091599, 2022). "Studies showed that ATF4 regulates HO-1 expression, and HO-1 stimulates autophagy and inhibits podocyte apoptosis induced by high glucose, however role of HO-1/ATF4 axis in podocytes of diabetic nephropathy remains unknown." (PMID 34157937, 2021). "We found that HO-1 expression was significantly increased in podocytes exposed to serum from DN mice suggesting activation of self-protection mechanism and ATF4 knockdown significantly reduced HO-1 expression, indicating HO-1 expression may be regulated by ATF4 in podocytes in diabetic nephropathy." (PMID 34157937, 2021). "Our present study utilizing in vitro and in vivo approaches shed light on the biology of ATF4/HO-1 pathway in regulating autophagy and apoptosis in renal podocytes in DN and suggests beneficial therapeutic effect of HO-1 agonist hemin in treating diabetic nephropathy." (PMID 34157937, 2021). "While induction of autophagy can inhibit podocyte injury in the context of high glucose levels, role of eIF2α/ATF4 pathway of autophagy in podocytes of mice with diabetic nephropathy is not clear." (PMID 34157937, 2021).
endometrial cancer (5 papers, 2018 to 2025). Primary or metastatic malignant neoplasm involving the endometrium (mucous membrane that lines the endometrial cavity). "Endometrial cancer cell proliferation decreased in vivo when the expression of activating transcription factor 4 (ATF4) was knocked down, as was the infiltration of M2 macrophages." (PMID 36403055, 2022). "On the other hand, a recent study showed that AN3CA and KLE endometrial cancer cells produce CCL2 via activating transcription factor 4 (ATF4), and that anti-CCL2 neutralizing antibody treatment suppresses macrophage infiltrations in subcutaneous tumors developed by AN3CA or KLE cells." (PMID 30483271, 2018). "We examined the protein expression of key components in PI3K/AKT, GCN2/ATF4, epithelial–mesenchymal transition and apoptosis pathways in ROR1‐positive endometrial cancer cell lines HEC‐1‐B, KLE, ARK1, RL95‐2 and Ishikawa, following treatment with GZD824 for 48 h." (PMID 39739675, 2025). "Moreover, ATF4 regulated macrophage infiltration by mediating the expression of CCL2, which ultimately led to the growth of endometrial cancer." (PMID 36403055, 2022). "Since high ATF4 expression correlates with high macrophage density in human endometrial cancer, up-regulation of this transcription factor in cancer cells might be another mechanism behind CCL2-induced TAM accumulation in endometrial cancer." (PMID 30483271, 2018).
endothelial dysfunction (5 papers, 2018 to 2025). In vascular diseases, endothelial dysfunction is a systemic pathological state of the endothelium (the inner lining of blood vessels) and can be broadly defined as an imbalance between vasodilating and vasoconstricting substances produced by (or acting on) the endothelium. "This is in line with other studies in both rats and mice which showed that endothelial dysfunction is associated with upregulation of pelF2α/ATF4/CHOP in mesenteric resistance arteries and aortas, albeit these studies were not performed during pregnancy." (PMID 35883766, 2022). "We found that Atf4 KO inhibited and Atf4 overexpression enhanced the increase in blood pressure and endothelial dysfunction induced by high salt intake in mice, while regulating the gut microbiota composition and VK2 expression." (PMID 33282868, 2020). "Recently, procyanidin B2 has been reported to improve endothelial dysfunction by downregulating ER stress-related signaling molecules, including CHOP, GRP78, and ATF4." (PMID 40276785, 2025). "In coronary endothelial cells, TMP prevents Ang-II-induced endothelial dysfunction by blocking the phosphorylation of PERK and upregulation of ATF4." (PMID 37268944, 2023).
esophageal cancer (5 papers, 2020 to 2022). A primary or metastatic malignant neoplasm involving the esophagus. "Future studies will be performed to elucidate the mechanism by how FCL transactivates ATF4 in esophageal cancer cells." (PMID 34195076, 2021). "Our previous study demonstrated that neddylation inhibition induced the accumulation of ATF4 to promote apoptosis in esophageal cancer cells." (PMID 32398095, 2020). "Moreover, ATF4 was previously shown to be upregulated in ESCC, contributing to the progression of esophageal cancer." (PMID 35707047, 2022). "Since MLN4924 treatment induced the accumulation of ATF4, a member of ATF/CREB subfamily, in esophageal cancer cells, we reasoned whether neddylation inhibition could affect the expression of other members of ATF/CREB subfamily, such as ATF3." (PMID 32398095, 2020).
iron deficiency (5 papers, 2018 to 2025). "ATF4 is a stress-responsive transcription factor modulating lipogenesis, fatty acid oxidation, lipoprotein metabolism, lipid storage, and inflammation; iron deficiency enhances ATF4-driven steatogenesis via HIF2α." (PMID 41149615, 2025). "Recent studies have found that iron deficiency induces hepatocyte insulin resistance and adipogenesis through the HIF2α-ATF4 signaling pathway." (PMID 39464186, 2024). "Importantly, ATF4 target genes are activated during iron deficiency to maintain mitochondrial function and to enable erythroid differentiation." (PMID 31033440, 2019).
liver fibrosis (5 papers, 2017 to 2024). "As a result of ancestral BPA exposure, the downregulation of hnf4a and overexpression of xbp1 and atf4 could have induced liver fibrosis and progressed the NAFLD to NASH phenotype in medaka." (PMID 38826193, 2024). "Ingenuity pathway analysis of microarray data obtained from mHSCs and Lx2 cells indicated that the most highly affected processes in DHA-treated cells were HSC activation/hepatic fibrosis, NRF2-mediated oxidative stress response and ATF4-mediated unfolded protein response (UPR)." (PMID 30622239, 2019).
mantle cell lymphoma (5 papers, 2017 to 2023). Mantle cell lymphoma is a rare form of malignant non-Hodgkin lymphoma affecting B lymphocytes in the lymph nodes in a region called the ``mantle zone''. "It has been demonstrated that ATF3 and ATF4 physically associate and activate the Noxa promoter in mantle cell lymphoma cells." (PMID 29352505, 2018). "In contrast, in both AML and mantle cell lymphoma (MCL) cell lines, ONC201 was shown to stimulate phosphorylation of GCN2 and eIF2α; however, eIF2α was found to be dispensable for ATF4 induction, suggesting that ONC201 stimulates a non-canonical ISR in hematologic malignancies." (PMID 36348393, 2022).
microphthalmia (5 papers, 2016 to 2022). Congenital or developmental anomaly in which the eyeballs are abnormally small. "Nevertheless, global ATF4-deficient mice have a complex phenotype that includes severe anemia, infertility, microphthalmia, growth retardation, and premature death." (PMID 30709400, 2019). "Additionally, although microphthalmia in ATF4-deficient mice precluded ONC in that genetic model, we found that daily dosing with ISRIB (10 mg/kg) for ten days can also provide partial neuroprotection in this model." (PMID 28440222, 2017). "The ATF4-/- mice develop severe microphthalmia with no recognizable lens, so they were unsuitable for this experiment." (PMID 27144303, 2016).